TRIM67 (tripartite motif containing 67)
Synonyms: TNL
Tractability: PROTAC: its protein half-life has been measured.
Gene: Protein-coding gene on chromosome 1 (231,162,058 to 231,221,565, forward strand). Ensembl gene ENSG00000119283.
Subcellular location: Cytoplasm; Cytoplasm, cytoskeleton
Gene Ontology:
Molecular function: zinc ion binding
Biological process: regulation of protein localization
Cellular component: cytoplasm; cytoskeleton
Genetic constraint (gnomAD): Loss-of-function variants: 36 observed, 56.19 expected, observed/expected ratio (o/e) 0.64, 90% interval 0.49 to 0.85. The upper end of that interval is the gene's LOEUF score, 0.85, which puts it in group 3 of 6, group 1 being the genes least tolerant of losing a copy. Missense variants: 963 observed, 954.74 expected, observed/expected ratio (o/e) 1.01, 90% interval 0.96 to 1.06. Synonymous variants: 478 observed, 417.54 expected, observed/expected ratio (o/e) 1.14, 90% interval 1.06 to 1.24.
Homologues: Orthologues: chimpanzee TRIM67 (99% identical), macaque TRIM67 (98% identical), dog TRIM67 (96% identical), rabbit TRIM67 (96% identical), pig TRIM67 (95% identical), rat Trim67 (92% identical), mouse Trim67 (92% identical), guinea pig TRIM67 (89% identical), tropical clawed frog trim67 (74% identical), zebrafish TRIM67 (65% identical). Paralogues in human: TRIM9 (62% identical), TRIM46 (22% identical), TRIM36 (22% identical), TRIM33 (15% identical), TRIM24 (15% identical), TRIM37 (14% identical), TRIM3 (14% identical), TRIM2 (14% identical), MID2 (14% identical), TRIM71 (14% identical), MID1 (13% identical), TRIM66 (12% identical), and 68 more.
Diseases named in the same sentence as TRIM67 in open-access papers:
TRIM67 is named in the same sentence as 46 diseases in open-access papers, as found by Europe PMC text mining. Sharing a sentence is not in itself a finding about the gene and the disease. The quoted sentences say what the papers report.
colorectal cancer (16 papers, 2020 to 2025). A primary or metastatic malignant neoplasm that affects the colon or rectum. "Conversely, TRIM67 downregulation in colorectal cancer is associated with poor survival, and its knockout in ApcMin mice increases the incidence and severity of colorectal tumors." (PMID 38225560, 2024). "The knockout of TRIM67 in mice results in the acceleration of colorectal cancer development, indicating its potential as a therapeutic target for this type of cancer." (PMID 38225560, 2024). "TRIM67 can regulate the progress of nonsmall cell lung cancer and colorectal cancer, and can inhibit the occurrence of inflammation by inhibiting the activation of NF-kB." (PMID 37686246, 2023). "The TRIM67 was reportedly downregulated in colorectal cancer and TRIM67 inhibited tumor proliferation and metastasis." (PMID 35795796, 2022). "Currently, little is known about TRIM67, although a previous study has proved that TRIM67 has been silenced in colorectal cancer, and is an important member of tumor suppressive TRIMs." (PMID 35887011, 2022). "The functional impact of promoter methylation in the transcriptional silencing of TRIM67 is furthermore underscored by the efficacy of the demethylation agent 5-aza-2 deoxycytidine to restore downregulated TRIM67 mRNA expression in colorectal cancer cells." (PMID 33066016, 2020). "In colorectal cancer, TRIM67 inhibits cancer cell proliferation, whereas in nonsmall cell lung cancer it promotes cancer cell proliferation." (PMID 37686246, 2023).
Obesity (5 papers, 2022 to 2025). Accumulation of substantial excess body fat. "Enhanced expression of TRIM67 activates hepatic inflammation to disturb lipid metabolic homeostasis and promote the progress of NAFLD induced by obesity, while the deficiency in TRIM67 is protective against these pathophysiological processes." (PMID 35806477, 2022). "Collectively, these results revealed the roles of TRIM67 deficiency in protecting against obesity-induced NAFLD development and progress." (PMID 35806477, 2022). "We also suggest that TRIM67 could be a potential diagnosis target; a person who is deficient in TRIM67 may also be susceptible to diet-induced obesity." (PMID 36012700, 2022). "As we found increased hepatic TRIM67 expression in obese mice, we presumed the loss function of TRIM67 would be beneficial for their livers, and also be protective against the progress of obesity-induced NAFLD." (PMID 35806477, 2022). "All of these findings display a tight correlation of PGC-1α and TRIM67 in response to obesity, and suggest a role for PGC-1α-TRIM67 axis in regulating liver function." (PMID 35806477, 2022). "In this study, we identified a novel role for TRIM67 in obesity-induced NAFLD development and progress." (PMID 35806477, 2022). "In conclusion, our data provide important insights into the protective role of TRIM67 in ileum and colon of obesity induced mice." (PMID 35887011, 2022). "All these findings revealed an essential role for TRIM67 in linking obesity and hepatic inflammation-regulated lipid metabolism." (PMID 35806477, 2022). "To understand the role of HFD and TRIM67 in intestinal pathology we used the KO mice and developed the obesity model and fed WT and KO mice with CTR diet as well as HFD for 14 weeks." (PMID 35887011, 2022). "In our study, we show that TRIM67 is a critical effector protein that links obesity and hepatic inflammation." (PMID 35806477, 2022). "In this study, we reveal potential implications between TRIM67 and the hypothalamic function responding to energy overuptake as well as a consideration for the therapeutic diagnosis of obesity." (PMID 36012700, 2022). "Since many TRIM family proteins play roles in inflammation, we presumed that TRIM67 would participate in hepatic inflammation to affect obesity-induced NAFLD progress." (PMID 35806477, 2022). "Finally, we show that the important transcription coactivator PGC-1α implicates in the response of hepatic TRIM67 to obesity." (PMID 35806477, 2022). "Since less hepatic steatosis and fibrosis indicate improved NAFLD progress, we combined the results from H&E staining and Masson staining and calculated the NAFLD activity score (NAS) to evaluate the development and progress of NAFLD induced by obesity in TRIM67 WT and KO mice." (PMID 35806477, 2022). "Our work also reveals a potential mechanism for TRIM67 to respond to obesity." (PMID 35806477, 2022). "A high-fat-diet/obesity could promote the expression of TRIM67 to activate hepatic inflammation, accumulate hepatic lipids and progress NAFLD, while deficiency in TRIM67 is protective against these processes." (PMID 35806477, 2022). "Moreover, our results further suggest a role for PGC-1α in regulating the response of TRIM67 to obesity." (PMID 35806477, 2022). "However, further clinical trials are needed to elucidate the mechanisms of TRIM67 as a protective marker because obesity related metabolic diseases have been increasing in recent years." (PMID 35887011, 2022). "Thus, we presumed that PGC-1α would implicate in the response of TRIM67 to obesity." (PMID 35806477, 2022). "Thus, we used Masson staining and Sirius Red staining to detect the collagen deposition in the liver, finding clearly visible signs of that in the obese TRIM67 WT liver but not in the obese TRIM67 KO liver, which indicated an attenuated hepatic fibrosis induced by obesity after TRIM67 deficiency." (PMID 35806477, 2022).
Obesity (continued). "Thus, we generated obesity/NAFLD mouse models through a high-fat-diet supplement, with both TRIM67 WT and KO mice." (PMID 35806477, 2022). "Furthermore, to confirm the protective effect of TRIM67 in inflammation, we treated the IPEC-J2 with NaHCO3 and PA to develop CTR and obesity model, respectively." (PMID 35887011, 2022). "TRIM67 is almost not expressed in the liver, but in the case of obesity, it is inducible, activating liver inflammation, lipid metabolism disorders, and promoting obesity-induced MAFLD." (PMID 37867509, 2023).
breast carcinoma (4 papers, 2021 to 2025). "Upregulation of TRIM67 was accompanied by upregulation of the pathways associated with breast cancer." (PMID 35795796, 2022). "Similar to the previous studies, we observed that TRIM67 was associated with BM in breast cancer and was a risk factor for a poor prognosis." (PMID 35795796, 2022). "The TRIM67 is a risk factor associated with brain metastases from breast cancer and it is considered a prognostic survival factor." (PMID 35795796, 2022). "The TRIM67 was identified as a factor associated with neurovascular metastasis, tumor metastasis, and prognostic survival in brain tumors in bioinformatics analysis of TCGA and breast cancer." (PMID 35795796, 2022). "Median overall survival time from the initial diagnosis of breast cancer was significantly shorter in the high TRIM67 group than in the low TRIM67 group (9.6 vs. 12.2 years, respectively, p = 0.031)." (PMID 35795796, 2022). "The TRIM67 upregulation was accompanied by upregulation of the integrated breast cancer pathway; however, it leads to the downregulation of the miRNA targets in ECM and membrane receptors and the miRNAs involved in DNA damage response pathways." (PMID 35795796, 2022). "The TRIM67 upregulation appeared to accompany the upregulation of the pathways related to breast cancer." (PMID 35795796, 2022). "Ultrasound and its prediction of TRIM67 play an important predictive role in neurovascular-related metastases from breast cancer." (PMID 35795796, 2022). "In TRIM67 upregulated tumors, the integrated breast cancer pathway was upregulated, whereas miRNA targets in ECM and membrane receptors and the miRNAs involved in DNA damage response pathways were downregulated." (PMID 35795796, 2022). "In this study, we explored the possible role of US as well as TRIM67 in the development of BM in breast cancer through a retrospective clinical cohort study and bioinformatics analysis." (PMID 35795796, 2022). "To further explore the possible functional pathways involved in TRIM67 in BM in patients with breast cancer, we used RNA sequencing data from patients with breast cancer who developed distant tumor metastasis in TCGA for Gene Set Enrichment Analysis (GSEA)." (PMID 35795796, 2022). "The results showed that in TRIM67-upregulated tumors, the integrated breast cancer pathway was upregulated, whereas the miRNA targets in ECM and membrane receptors and miRNAs involved in DNA damage response pathways were downregulated." (PMID 35795796, 2022). "In this study, TRIM67 was upregulated in patients with BM from breast cancer and DM." (PMID 35795796, 2022). "The TRIM67 expression is associated with DM in breast cancer; therefore, US combined with examination of TRIM67 expression may have a better predictive function in breast cancer metastases." (PMID 35795796, 2022). "Additionally, we will further investigate the mechanism of TRIM67 in breast cancer metastasis at the basic experimental level." (PMID 35795796, 2022). "Furthermore, we showed that TRIM50 inhibited pancreatic cancer invasiveness and distant metastasis and reversed the EMT process, which was supported by the roles of TRIM67 as tumor suppressor in breast cancer and lung cancer." (PMID 34568024, 2021). "In luminal B breast cancer, our data show that both WWOX and TRIM67 remain underutilized in clinical practice." (PMID 41007296, 2025). "The nomogram of six variables—stage, TRIM67, tumor size, N, age, and HER2 status—were biomarkers of the likelihood of breast cancer metastasis." (PMID 35795796, 2022). "The nomogram constructed from six variables—stage, TRIM67, tumor size, N, age, HER2 status—is an appropriate predictor to estimate the occurrence of breast cancer metastasis." (PMID 35795796, 2022). "In addition, ROC analysis revealed that the four genes had higher AUC values for predicting the diagnosis of breast cancer (TBC1D24, AUC = 0.798; TRIM67, AUC = 0.711; ZDHHC9, AUC = 0.810; QRSL1, AUC = 0.801)." (PMID 37875591, 2023).
glioma (4 papers, 2020 to 2026). A benign or malignant brain and spinal cord tumor that arises from glial cells (astrocytes, oligodendrocytes, ependymal cells). "In addition, auto-antibodies against TRIM9/SPRING and TRIM67/TNL have been described as a potential high-risk paraneoplastic biomarker, and TRIM67/TNL is associated with higher cell motility and reduced cell adherence in glioma cells." (PMID 39205302, 2024). "A series of genes such as EN1, S100A4, ANXA1, PDPN, IGFBP2 and CHI3L1 were upregulated in radiotherapy treated glioma patients, while other genes such as PRLHR, SFRP2, BRINP1, TRIM67, LHX5, KCNIP2 and NSG2 were downregulated." (PMID 34852024, 2021).
lung cancer (4 papers, 2020 to 2025). A malignant neoplasm involving the lung. "To elucidate the mechanism by which TRIM67 enhances the migration/invasion of lung cancer cells, we detected the expression of EMT-related proteins by western blotting." (PMID 31956370, 2020). "Here, we demonstrated that TRIM67 is expressed in NSCLC and multiple lung cancer cell lines." (PMID 31956370, 2020).
non-small cell lung carcinoma (4 papers, 2020 to 2024). A group of at least three distinct histological types of lung cancer, including non-small cell squamous cell carcinoma, adenocarcinoma, and large cell carcinoma. "We previously reported that TRIM67 positively regulates the Notch pathway to increase the migration, invasion, and proliferation of non-small cell lung cancer (NSCLC) cells." (PMID 38434968, 2024). "The TRIM67 promoted the progression of non-small cell lung cancer through the Notch pathway, including promoting cell proliferation, migration, and EMT." (PMID 35795796, 2022). "The down regulation of TRIM67 may contribute to the over-activation of Ras signal pathway and overgrowth of non-small cell lung cancer cells, leading to the malignant progression of tumor." (PMID 31907037, 2020). "However, upregulation of TRIM67 expression increased apoptosis in non-small cell lung cancer cells." (PMID 35795796, 2022).
astrocytoma (3 papers, 2022 to 2026). "Validation of 6 biomarkers with the highest importance score in TCGA and CGGA cohorts revealed that HS3ST1, and CNN3 were overexpressed in astrocytoma, while SLAIN1, ABTB2, TRIM67 and DRG2 were overexpressed in oligodendroglioma." (PMID 35287567, 2022). "Analysis of the SHAP values for the remaining genes revealed that increased expression of ZDHHC18, HDAC1, and TUBB6 enhances the probability of predicting astrocytoma, while elevated expression of TERT, TRIM67, NOG, KCNIP2, and KCNJ11 increases the probability of predicting oligodendroglioma." (PMID 40867242, 2025).
lymph node metastasis (3 papers, 2020 to 2022). "TRIM67 expression was associated with tumor size, lymph node metastasis, p-TNM stage, cancer cell differentiation, and poor prognosis." (PMID 31956370, 2020). "In this study, we showed that the expression of TRIM67 was associated with a range of clinicopathological features, such as tumor size, differentiation, lymph node metastasis, p-TNM staging, and prognosis." (PMID 31956370, 2020). "Microcalcifications on US findings correlated with TRIM67 expression, and a higher blood flow grade, positive prediction of lymph node metastasis, and larger tumor size corresponded with higher TRIM67 expression." (PMID 35795796, 2022).
Non-Alcoholic Fatty Liver Disease (3 papers, 2022 to 2025). "TRIM family proteins are known to regulate macrophage-mediated immune responses, and TRIM67 knockdown inhibits macrophage recruitment in the liver of mice with nonalcoholic fatty liver disease." (PMID 40572155, 2025). "In this respect, it is important to note that TRIM67/TNL, undetectable in the liver under normal conditions, can be induced in this organ in conditions of obesity, where it activates hepatic inflammation, exacerbating the progress of non-alcoholic fatty liver disease (NAFLD) found in this pathology." (PMID 39205302, 2024).
oligodendroglioma (3 papers, 2022 to 2026). A well-differentiated (WHO grade II), diffusely infiltrating neuroglial tumor, typically located in the cerebral hemispheres. "TRIM67 is known to be a highly expressed gene in oligodendrogliomas." (PMID 40867242, 2025).
Anxiety (1 paper, 2018). Intense feelings of nervousness, tension, or panic often arise in response to interpersonal stresses. "Normal behaviors in these tests indicate loss of Trim67 does not detectably impact sensory abilities, general locomotion, or anxiety behaviors." (PMID 29911180, 2018).
anxiety disorder (1 paper, 2018). A category of psychiatric disorders which are characterized by anxious feelings or fear often accompanied by physical symptoms associated with anxiety. "Indeed, a small GWAS of patients with neuroticism, a personality trait that often occurs with major depression and anxiety disorders, identified variations in several genes, including TRIM67." (PMID 29911180, 2018).
brain infarct (1 paper, 2023). "TRIM67 overexpression decreased brain infarct size and neurological impairment and improved cognitive performance in MCAO/R mice, all of which have potential translational implications." (PMID 37248543, 2023).
brain tumor (1 paper, 2022). "Tripartite motif-containing protein 67 (TRIM67) was identified and the differential; in addition, the survival analyses of the TCGA database revealed that it was associated with brain tumor metastases and overall survival prognosis." (PMID 35795796, 2022).